STAT3 (signal transducer and activator of transcription 3)
Diseases named in the same sentence as STAT3 in open-access papers (continued):
Sharing a sentence is not in itself a finding about the gene and the disease.
breast cancer (continued). "It is feasible that STAT1 and STAT3 may have differing roles in different breast cancer subgroups dependent on whether they are hormonally or growth factor-driven." (PMID 24728078, 2014). "A number of studies have examined the activation state of STAT3 in primary breast cancers." (PMID 24762632, 2014). "CX-4945 also decreases IL-6 serum levels and STAT3 levels in an inflammatory breast cancer model." (PMID 25153725, 2014). "Interestingly, STAT3 is also a critical component downstream of the y box binding protein YB-1 in Her2 driven breast cancer as well as renal cancer." (PMID 24722453, 2014). "Furthermore, high levels of STAT3 are a poor survival predicator in patients with breast cancer with lymph node metastasis." (PMID 25013518, 2014). "Therefore, we conclude that SH003 suppresses highly metastatic breast cancer growth and metastasis by inhibiting STAT3-IL-6 signaling path." (PMID 24976685, 2014). "STAT3 activation is also associated more with advanced breast cancer, as opposed to STAT5, which is more prominently involved in tumor initiation." (PMID 25153725, 2014). "Thus, COX-2-overexpressing breast cancer cells upregulate IDO expression in fibroblasts through the PGE2/EP4/STAT3 pathway." (PMID 25060643, 2014). "Initially we tested the effect of STAT3 in HER2-positive breast cancer." (PMID 24297508, 2014). "In addition, Stat3 also up-regulates other important downstream genes that contribute to cell proliferation, cell survival and angiogenesis in breast cancer." (PMID 24416452, 2014). "Importantly, Stat3 phosphorylation (Tyr705) was observed in nuclei in approximately 35% of breast cancer tissues." (PMID 24416452, 2014). "Many data have established a pivotal role for STAT3 during breast cancer onset and progression." (PMID 25026286, 2014). "Moreover, we observed significant increases in ERK and STAT3 phosphorylation in 4T1.2 breast cancer cells on CXCL12 induction." (PMID 24886617, 2014). "Furthermore, if the activation of STAT3 plays a role in breast cancer stem-like cells then inhibition of this pathway represents a rational strategy to target the breast cancer stem cell-like populations." (PMID 24376586, 2013). "The constitutive activation of STAT3 signaling that leads to regulation of hTERT pathway may provide novel therapeutic targets for human breast cancer stem cells." (PMID 24386318, 2013). "In addition, recent studies reported that STAT3 is one of the key signaling molecules that maintain breast cancer stem cell population, and that knockdown of STAT3 with shRNA markedly repressed mammary tumorigenesis in mice." (PMID 23326564, 2013). "Furthermore, we observed a positive correlation in a breast cancer series between STAT3 and ZIP6 (P=0.007), agreeing with the known association of STAT3 with breast cancer progression." (PMID 23919497, 2013). "A recent study reported that CD44+ tumor-initiating breast cancer cells had preferential activation of STAT3, suggesting that STAT3 may be a potential therapeutic target in breast cancer." (PMID 23326564, 2013). "Here, we elucidated the VEGFR2-activated STAT3 signaling pathway in human breast cancer cells." (PMID 23731702, 2013). "Furthermore, both breast cancer mutations implicated an increased tyrosine phosphorylation of the critical FGFR2 substrate FRS2 and an increased MEK1/2 and STAT3 activation in response to FGF1 stimulation leading to an accelerated cell signaling." (PMID 23527311, 2013). "Furthermore, in breast cancer, abrogation of STAT3 activation inhibited tumor formation in the mammary fat pad of a syngeneic model." (PMID 24380387, 2013). "Since hTERT expression levels were up-regulated in the pSTAT3 activated breast cancer cell lines, we next wished to determine whether STAT3 is the genuine cellular factor that regulates hTERT." (PMID 24386318, 2013).
breast cancer (continued). "Therefore, these novel sorafenib analogues, SC-1 and SC-43, induced apoptosis through SHP-1-dependent STAT3 inactivation and demonstrated more potent apoptotic effects than sorafenib in human breast cancer cells." (PMID 23938089, 2013). "In addition to direct transcriptional effects mediated by nuclear PR, other authors have shown that progestins can rapidly activate the Src/Ras/MAPK, PI3 kinase/Akt, and JAK2/Stat3 signaling pathway in breast cancer and mammary epithelial cells." (PMID 23484104, 2013). "However, little is known how STAT3 is regulated in the cancer stem cell and by which mechanisms STAT3 contributes to poor prognosis in aggressive breast cancer." (PMID 24386318, 2013). "A recent study demonstrated significantly elevated expression of uPA in highly invasive basal-like breast cancer in a CD44-dependent manner, and a protein microarray study of primary breast cancer tissue found significant correlation between expression levels of uPA and STAT3." (PMID 23326564, 2013). "Targeting p-STAT3 by enhancement of SHP-1 activity may be a novel therapeutic approach for breast cancer." (PMID 23938089, 2013). "Our study suggests that repression of STAT3 signaling by targeting CD44 may be a key molecular mechanism of BXL0124-induced inhibition of breast cancer invasion, a critical step in cancer progression." (PMID 23326564, 2013). "In addition, Stat3 was identified as a critical node in self-renewal in breast cancer tumor-initiating cells." (PMID 24376586, 2013). "Because stimulation with IL-6 induces IL-19 expression, there may be positive feedback between IL-6 and IL-19 that elicits the STAT3 signal and the progression of breast cancer." (PMID 23710200, 2013). "Notably, it was demonstrated that CD44 positive breast cancer stem cells had preferential activation of STAT3, suggesting STAT3 as a potential therapeutic target for human breast tumors." (PMID 24386318, 2013). "Constitutively activated STAT3 has been documented as a key driver of breast cancer growth and metastasis, and we have previously reported that STAT3 knockdown in breast cancer cells diminishes CXCR4 expression and inhibits breast cancer growth and metastases in an in vivo tumor transplant model." (PMID 23484027, 2013). "In addition, STAT5 and STAT3 mediate opposing effects on several key target genes in breast cancer cells, with STAT5 exerting a dominant role." (PMID 24376586, 2013). "Moreover, IL-6/STAT3 signaling is required for growth of CD44+CD24- stem cell-like breast cancer cells, a type of cells that play an important role in the clinical behavior of triple-negative breast cancer (TNBC)." (PMID 23938089, 2013). "Here, we report that AMD3465 triggers a reduction in breast cancer cell invasiveness in vitro, and promotes marked changes in oncogenic signaling proteins including a reduction in STAT3, JAK2, AKT, and CXCR4 phosphorylation and the reduced expression of GSK3 and cMYC." (PMID 23484027, 2013). "STAT3 is constitutively activated in many common human cancers, including breast cancers." (PMID 23938089, 2013). "Activated STAT3 signaling also has been shown to induce expression of survivin expression, a direct downstream target of STAT3 and confer resistance to apoptosis in human breast cancer cells." (PMID 23938089, 2013). "This indicates that STAT3 is required for the hTERT gene expression in the breast cancer cells." (PMID 24386318, 2013). "In the same paper, authors also showed that a small molecule Stat3 inhibitor could reduce breast cancer tumor-initiating cells and improve recurrence free survival in a human-xenograft model." (PMID 24376586, 2013). "Furthermore, LLL12 inhibited Twist1, Notch-1, and Notch-3 expression in ALDH+ breast cancer stem-like cells, which have recently been reported as STAT3 or Interleukin-6 target genes." (PMID 24376586, 2013).
breast cancer (continued). "However, the molecular mechanisms by which STAT3 is promoting cancer stem cell traits in breast cancer, as well as the potential contributions of STAT3 to metastasis, have yet to be defined." (PMID 24386318, 2013). "miR-20b modulates VEGF expression by targeting HIF-1α and STAT3 in MCF-7 breast cancer cells." (PMID 24130753, 2013). "To examine whether LLL12 might effectively target the ALDH+ subpopulation, we determined the effect of this STAT3 inhibitor on the percentage of ALDH expression in breast cancer cells." (PMID 24376586, 2013). "STAT3 is also a downstream target of receptors in the epidermal growth factor receptor (EGFR) family, and several of these have been implicated in the stimulatory effect of wound healing on HNSCC cells and breast carcinoma." (PMID 23351302, 2013). "Tyr23 phosphorylation of Anxa2 could activate Stat3 and phosphorylation Stat3 localization in the nucleus of breast cancer SK-BR-3 cells." (PMID 23691485, 2012). "STAT3 activity (in absence of STAT5 activity) has been shown previously to be present in 40% of human breast cancers and has been linked to higher grade and lymph node metastasis." (PMID 22689141, 2012). "In the current study, we sought to determine whether STAT3 mediated tamoxifen resistance of breast cancer stem cells in vitro." (PMID 23554768, 2012). "To address whether PTPMeg2 regulates STAT3 dephosphorylation in human tumors, we examined the correlation of pSTAT3 level and expression of PTPMeg2 in human breast cancers." (PMID 22394684, 2012). "In this study, we demonstrated that XZH-5 could inhibit STAT3 phosphorylation in pancreatic and breast cancer cell lines expressing constitutive STAT3." (PMID 23056374, 2012). "Stat3 function as an upstream activator of c-Myc in breast cancer has already been shown." (PMID 22583478, 2012). "We found that in the nucleus of breast cancer cells, ErbB-2 assembles a transcriptional complex in which it functions as a coactivator of the signal transducer and activator of transcription 3 (Stat3) to promote the expression of cyclin D1, another gene known to induce breast cancer proliferation." (PMID 22356700, 2012). "It is conceivable that disruption of the feedback loop between Rac1 and E-cadherin adherens junctions could lead to aberrant STAT3 activation in breast cancer." (PMID 22689141, 2012). "In addition, HSE treatment inhibited STAT5b/IGF-1R and STAT3/VEGF-dependent luciferase activities in breast cancer cells." (PMID 22792362, 2012). "We have demonstrated, at the breast cancer tissue level, a link between STAT3 and Rac proteins." (PMID 22689141, 2012). "However, little is known about the effects of Tyr23 phosphorylation of Anxa2 on the proliferation and invasion abilities of breast cancer cells and on the localization of the phosphorylation signal transducer and activator of transcription (Stat3)." (PMID 23691485, 2012). "We sought to determine whether STAT3 mediated tamoxifen resistance of breast cancer stem cells in vitro." (PMID 23554768, 2012). "Stat3 in conjunction with NF-kB is a transcriptional regulator of the chemokine RANTES which was recently shown to be a potent mediator of metastatic spread of breast cancer cells." (PMID 22140473, 2011). "In order to determine Stat3 target genes that may be involved in migration and metastasis, we identified those genes that were differentially expressed in primary breast cancer samples as a function of pStat3 levels." (PMID 22140473, 2011). "Here we report the ability of siRNA-mediated Src knock-down alone, and simultaneous knock-down of Src and Stat3 and/or cMyc to inhibit the neoplastic phenotype of a highly metastatic human model breast cancer cell line, MDA-MB-435S, a widely used model for breast cancer research." (PMID 21541295, 2011).
breast cancer (continued). "In order to identify potential Stat3 target genes in breast cancer which may regulate invasion, migration and metastasis we sought to identify genes that were differentially expressed in tumor samples as a function of pStat3 as assessed by IHC." (PMID 22140473, 2011). "In summary, we have identified ATX as a putative novel Stat3 target gene in breast cancer." (PMID 22140473, 2011). "A recent study has demonstrated the role of STAT3 in BM from breast cancer." (PMID 22567347, 2011). "In addition, side-population breast cancer stem-like cells express and require persistently activated Stat3 for viability and maintenance." (PMID 22140473, 2011). "Given that tumors are heterogeneous, we hypothesized that a subset of breast cancer cells expressing activated Stat3 were capable of metastasizing to the axillary lymph nodes." (PMID 22140473, 2011). "The details of STAT3's interaction with EGFRvIII are currently unknown; however, evidence from breast cancer cell lines suggests that EGFRvIII may translocate to the nucleus and alter the binding of STAT3 to DNA." (PMID 22190972, 2011). "Furthermore, they showed that ectopic expression of Caveolin-1 or knockdown of STAT3 reduces the invasive features of breast cancer cells in vitro and brain colonization in vivo." (PMID 22567347, 2011). "Other studies have suggested that MMP-7 could be a direct target for STAT3 in gastric and breast cancer cells, which is consistent with our conclusion in pancreatic cancer cells." (PMID 21991388, 2011). "Moreover STAT3 is a potent mediator of pro-inflammatory interleukin 6 (IL-6) that was shown to induce EMT phenotype in human breast cancer cells." (PMID 22194995, 2011). "Furthermore, the interleukin-6 ligand (IL-6) which was recently shown to be a principal regulator of Stat3 activation in breast cancer, was found to be elevated in both MCF10A-Ras and MMTV-K-Ras tumors." (PMID 20929542, 2010). "Stat3 is found to be constitutively phosphorylated to high levels in >50% of breast cancer derived cell lines and in >30% of breast adenocarcinomas and may be a poor prognostic indicator." (PMID 20929542, 2010). "Nevertheless, comparison of the EC50 values of Cpd188 for the two groups of breast cancer cell lines indicated that, similar to Cpd 3 and Cpd30, Cpd188 showed preferential activity against cell lines with constitutive Stat3 activity (p = 0.014, Student's t-test)." (PMID 19274102, 2009). "STAT3 is a transcription factor that stimulates cell proliferation and survival, and frequently exhibits constitutive activity in different types of human tumors including prostate, lung and breast cancers." (PMID 19744341, 2009). "This approach identified for the first time 3 novel lead compounds that competitively inhibit Stat3 binding to its pY-peptide ligand, that are selective for Stat3 vs. Stat1 and that also induce apoptosis preferentially of breast cancer cells lines with constitutively activated Stat3." (PMID 19274102, 2009). "In addition, we show that BITC can prevent the induction of STAT3 activation by Interleukin-6 in MDA-MB-453 breast cancer cells." (PMID 19712481, 2009). "In addition, in human HNSCC and breast cancer cell lines EGCG inhibits the constitutive activation of the transcription factor Stat3, which also lies downstream of EGFR." (PMID 19325845, 2008). "Furthermore, EGCG inhibits the production of VEGF in human HNSCC and breast cancer cells, apparently by inhibiting both the activation of Stat3 and NF-κB in these cells." (PMID 19325845, 2008). "Thus, inhibiting Stat3 activity or expression is likely to be an important therapeutic modality for a number of malignancies, including breast cancer." (PMID 17531096, 2007). "It has been suggested in murine models of breast cancer that aberrant Her2neu signaling may mediate Stat3 activation." (PMID 17531096, 2007).
breast cancer (continued). "However, our results imply that in the development of therapeutic strategies for blocking Stat3 in breast cancer cells, the strong dependence on the cellular context that this factor activity displays should be taken into account." (PMID 17925034, 2007). "This hypothesis was confirmed by the ability of conditioned medium of mammary tumor primary cultures to induce Stat3 phosphorylation, activity that was prevented by pretreatment with LIF-blocking antibody." (PMID 17925034, 2007). "LIF is overexpressed in mouse mammary tumors, where it acts as the main Stat3 activator." (PMID 17925034, 2007). "However, elevated Stat3 tyrosine phosphorylation and DNA-binding activity have been reported in breast cancer cell lines." (PMID 17925034, 2007). "We propose that the IL-6/gp130/Jak signaling pathway plays a critical role in Stat3 activation in human breast cancer and that blockade of this pathway may be an important therapeutic modality in breast cancer." (PMID 17531096, 2007). "For further analysis of the hypothesis that LIF-mediated signaling would be a determinant for Stat3 activation in mouse mammary tumors, the capacity of LIF to induce tyrosine phosphorylation of Stat3 was analyzed in cultured cells." (PMID 17925034, 2007). "Indeed, STAT3 activation has been previously implicated in the pathogenesis of AIDS-NHL, and in many other cancers including breast cancer, multiple myeloma, head and neck cancer, leukemias, lymphomas, lung cancer and prostate cancer." (PMID 17324269, 2007). "Here we have tested the hypothesis that locally produced LIF can be responsible for Stat3 activation in mouse mammary tumors." (PMID 17925034, 2007). "Thus, in contrast to other reports, we did not observe any effect of either EGFR/Her2 or Src inhibition on Stat3 activation in breast cancer-derived cell lines." (PMID 17531096, 2007). "Here, we examined the mechanisms of Stat3 phosphorylation in breast cancer." (PMID 17531096, 2007). "Constitutive activation of STAT3 has been observed in breast cancer, prostate cancer and leukaemia." (PMID 15354212, 2004). "Therefore, dual‐targeting APE1 redox activity and STAT3 could be a promising new therapeutic approach against breast cancer." (PMID 41090323, 2025). "Furthermore, CD36 in interaction with FABP4 that enhance the import of free fatty acids from adipocytes in the tumor microenvironment leads to activation of STAT3 signaling, metabolic reprogramming with a shift toward beta oxidation and promoting breast cancer progression." (PMID 39920872, 2025). "Therefore, the APE1 redox domain and STAT3 appear promising targets for a new possible combined treatment, which could be a more efficient strategy against breast cancer." (PMID 41090323, 2025). "Recently, PRMT6 has been found to promote breast cancer metastasis through asymmetrical di-methylation of the signal transducer and activator of transcription 3 (STAT3), which activates downstream signaling in the IL-6/STAT3 pathway, contributing to tumor metastasis and invasion." (PMID 39908270, 2025). "Besides, A study found that CAF-derived conditioned media could induce breast cancer’s cell growth and radio-resistance through secreted interleukin six and activated the signal transducer and activator of transcription 3 (STAT3) signaling pathway." (PMID 40661314, 2025). "TAM-specific extracellular signal-regulated kinase (ERK)/STAT3 activation, increased vascular endothelial growth factor (VEGF) and arginase- 1 (ARG1) production, and HIF- 1a stabilization have all been implicated in lactate-induced TAM polarization and its protumorigenic effects in breast cancer." (PMID 40295451, 2025).